RNU6-902P (RNA, U6 small nuclear 902, pseudogene)
Gene: Small nuclear RNA gene on chromosome 19 (44,085,213 to 44,085,303, reverse strand). Ensembl gene ENSG00000253021.
Homologues: Orthologues: chimpanzee U6 (97% identical), guinea pig U6 (78% identical), dog U6 (75% identical), dog U6 (74% identical), dog U6 (69% identical), rat LOC120097204 (68% identical), mouse Gm55634 (65% identical). Paralogues in human: RNU6-140P (87% identical), RNU6-641P (86% identical), RNU6-698P (86% identical), RNU6-748P (86% identical), RNU6-891P (86% identical), RNU6-949P (86% identical), RNU6-955P (86% identical), RNU6-1042P (85% identical), RNU6-1158P (85% identical), RNU6-422P (85% identical), RNU6-1036P (84% identical), RNU6-1316P (84% identical), and 1285 more.